SHH (sonic hedgehog signaling molecule)
Diseases named in the same sentence as SHH in open-access papers (continued):
Sharing a sentence is not in itself a finding about the gene and the disease.
medulloblastoma (continued). "Together these data show that Stat3 is required for SHH signaling and that IL-6 expression is elevated in males which enhances SHH signaling and may contribute to the Stat3 and sex-dependent onset of medulloblastoma." (PMID 31683879, 2019). "In the context of medulloblastoma formation and other tumors involving Wnt/β-catenin and SHH signaling mechanisms, such elevated CK1 kinase activity and the loss of its control can lead to hyperstimulation of these signaling pathways, thereby supporting tumor formation." (PMID 29222110, 2018). "These substrates may include other drivers of SHH-medulloblastoma tumorigenesis, in addition to GLI1." (PMID 30314361, 2018). "The fact that CK1 activity is needed in Wnt/β-catenin and SHH signaling suggested that mutations in DDX3X might affect CK1 activity and that this could be the reason why they cluster in the Wnt and SHH medulloblastoma tumor groups." (PMID 29222110, 2018). "In turn, this possibility suggests that mechanisms involving interaction between GLI1 and PIN1 may represent potential therapeutic targets in SHH-driven medulloblastoma tumorigenesis." (PMID 30314361, 2018). "In agreement with an AMPKα2-specific function in SHH medulloblastoma and the fact that the cerebellar granular neuron progenitor cell (CGNP) is the “cell of origin” in SHH-driven medulloblastoma, AMPKα2 is expressed at higher level than AMPKα1 in cerebellar granule neurons." (PMID 30360486, 2018). "Recent work has provided evidence that implicates PIN1 in SHH-medulloblastoma." (PMID 30314361, 2018). "In conclusion, notwithstanding that other AMPK substrates may also contribute to the pro-tumorigenic role of AMPKα2 in medulloblastoma, these results further support the hypothesis of a critical role for the SHH/AMPK/CNBP axis in SHH-driven medulloblastoma." (PMID 30360486, 2018). "Interestingly, MYCN drives either SHH-dependent or SHH-independent medulloblastoma as a consequence of the timing of its oncogenic expression from embryonic or postnatal cerebellar stem cells, respectively." (PMID 28333115, 2017). "Atoh1/Math1 is a bHLH transcription factor required for SHH medulloblastoma development." (PMID 28333115, 2017). "While Daoy and UW228 are routinely used in studies of medulloblastoma, their exact subtype is still poorly understood, with suggestions that Daoy may belong to the SHH subtype." (PMID 28248256, 2017). "Additionally, forced expression of wild-type MYCN can promote SHH-independent medulloblastoma development when driven from the brain-specific Glutamate transporter 1 (Glt1) promoter in the Tet-inducible Glt1-tTA;TRE-MYCN/Luciferase (GTML) transgenic model." (PMID 28333115, 2017). "SHH is usually inactivated in adult human tissues but aberrant activation of the hedgehog pathway has been reported in a number of cancers, with it being noted as a driver in medulloblastoma." (PMID 28978082, 2017). "About 30% of medulloblastoma tumors belong to the sonic hedgehog (SHH) subgroup." (PMID 29186899, 2017). "Thus, the current classification of medulloblastomas include Wnt, sonic hedgehog (SHH) and group 3 and 4 subtypes." (PMID 28228863, 2017). "Thus, in the majority of SHH medulloblastoma, Sufu protein levels will be low due to the constitutive activation of Hh signaling." (PMID 27234298, 2016). "Several reports have shown that the SHH signalling system is highly activated in medulloblastoma." (PMID 27601167, 2016). "The sonic hedgehog (SHH) signaling pathways are important in the carcinogenesis of medulloblastoma." (PMID 27807473, 2016). "A medulloblastoma sample of the SHH subtype also expressed high level of GLI1." (PMID 27825128, 2016).
medulloblastoma (continued). "Similarly, in a mouse model of SHH-driven medulloblastoma, rare quiescent Sox2+-marked adult neural stem cells were found to be resistant to anti-mitotic and SHH-targeted therapy and responsible for recurrence after treatment." (PMID 26839398, 2016). "The sonic hedgehog (SHH) signalling pathway plays the important role in medulloblastoma (MB)." (PMID 27601167, 2016). "Tumor subtypes are currently identified by biomarker (such as HER2+ or HER2- breast cancers) or signature gene expression, or signaling pathway activity (such as Sonic Hedgehog (SHH) or Wnt pathways in medulloblastoma) within a small biopsy or region of a resected tumor." (PMID 27608848, 2016). "Indeed, genome sequencing studies by our group and others have identified DDX3X mutations in over 50% of Wingless (WNT) subgroup medulloblastomas in children and upwards of 60% of Sonic hedgehog (SHH) subgroup medulloblastomas in adults." (PMID 27058758, 2016). "Consistent with the use of Shh and Mycn genes to create the mouse tumors, a clustering analysis of highly variable genes among human medulloblastoma subgroups demonstrated that the distinct cluster of BarTeL medulloblastoma samples was closest to that of human SHH subgroup medulloblastomas." (PMID 27310018, 2016). "In particular, human medulloblastomas of the SHH subgroup, accounting for ~30% of all medulloblastomas, arise mostly due to mutations in the PTCH1 receptor, the transmembrane activator Smoothened, the signal transduction modulator SUFU and transcriptional regulator GLI2." (PMID 25901736, 2015). "A number of experimental findings suggest that the positioning of ADCY3 in primary cilia anatomy may support a cooperative role for cAMP regulation in SHH pathway dependent medulloblastoma-genesis." (PMID 26283963, 2015). "Although subgroup stability at relapse supports the use of diagnostic biopsy to define subgroup-directed therapies at relapse (e.g., SHH pathway inhibitors), we now understand that medulloblastomas display unique and emergent biology at relapse, which cannot be predicted at diagnosis." (PMID 25533335, 2015). "We found that Dicer restricts SHH medulloblastoma development in Ptch1+/- mice." (PMID 26091048, 2015). "In summary, while Dicer is essential for proper cerebellar development and homeostasis, it restrains SHH medulloblastoma development suggesting that it might be haploinsufficient for medulloblastoma suppression." (PMID 26091048, 2015). "Since this neighborhood contains neuronal differentiation gene sets, medulloblastoma subgroups (WNT <SHH < Group 3< Group 4) may represent stages of a neuronal differentiation continuum." (PMID 25412507, 2014). "Furthermore, transgenic mice overexpressing SHH develop various tumors, such as basal cell carcinoma, medulloblastoma and breast carcinoma." (PMID 23835807, 2013). "This unique postnatal expansion of neuronal precursors is driven in large part by the mitogen Sonic Hedgehog (SHH), and deregulation of the SHH signaling pathway in GCPs gives rise to a subset of medulloblastoma, which is the most prevalent metastatic brain tumor of childhood." (PMID 24303070, 2013). "A subset of medulloblastomas, the most common brain tumor in children, is hypothesized to originate from granule neuron precursors (GNPs) in which the sonic hedgehog (SHH) pathway is over-activated." (PMID 22808009, 2012). "Interestingly, in mice a link between IFNγ and SHH signaling was observed as an ectopic expression of IFNγ was shown to induce medulloblastoma formation via SHH overexpression." (PMID 23162429, 2012).
medulloblastoma (continued). "In this case, the genesis of medulloblastoma is driven by SHH pathway activation." (PMID 22277186, 2012). "Interestingly, ectopic expression of IFNγ during early stages of CNS development induces medulloblastomas via SHH overexpression pointing towards a general dysregulating effect of IFNγ on NSPCs during development or disease." (PMID 21371330, 2011). "SHH is a critical mitogen for medulloblastoma precursor cells." (PMID 24212955, 2011). "The data enabled us to address the question of whether circadian clock genes were expressed in medulloblastoma tissue samples and if so, whether the transcription of these genes was differentially expressed among the four consensus subgroups of medulloblastoma, Group 3, Group 4, SHH, and WNT." (PMID 40002179, 2025). "Interestingly, recent studies have shown that CUR inhibits the Hh pathway in several other cancers, such as breast cancer, gastric cancer, and medulloblastoma, by downregulating the expression of SHh, PTCH1, and GLI1/GLI2, leading to reduced cell proliferation, invasion, and migration." (PMID 39457084, 2024). "Medulloblastoma (MB) tumors likely arise from neuronal progenitors in the cerebellum, and we hypothesized that the heterogeneity observed in MBs with sonic hedgehog (SHH) activation could be due to differences in developmental pathways." (PMID 38191555, 2024). "Notably, the combination of CD532, which disrupts the interaction between AURK and MYCN, and verteporfin, a YAP inhibitor, was associated with a dramatic suppression of tumor growth both in vitro and in vivo and an increased survival of SHH-activated medulloblastoma-bearing mice." (PMID 37568705, 2023). "Hence, the cMET inhibitor foretinib was investigated for the treatment of this subgroup of medulloblastoma, and it showed acceptable penetration of the blood–brain barrier and significant suppression of the proliferation and migration of SHH-activated medulloblastomas in xenograft mouse models." (PMID 37568705, 2023). "Indeed, inhibiting polo-like kinase (PLK) and Aurora kinase (AURK), which are pivotal for the G2/M transition of the cell cycle, using BI-2536 and VX-680 (tozasertib), respectively, resulted in increased apoptosis of SHH-driven medulloblastoma cells in vitro and in vivo." (PMID 37568705, 2023). "In addition, an actively recruiting randomized controlled phase II trial (PersoMed-I, NCT04402073) by the European Organisation for Research and Treatment of Cancer aims to assess the efficacy of sonidegib with reduced-dose radiotherapy in post-pubertal patients with SHH-activated medulloblastomas." (PMID 37568705, 2023). "In contrast to SHH-activated medulloblastoma, activating mutations are generally absent in ATRT–SHH, suggesting other mechanisms may be operative." (PMID 35501487, 2022). "While a reduction in SHH signaling induces cerebellar structural abnormalities, such as hypoplasia in various genetic disorders, the constitutive activation of SHH signaling often induces medulloblastoma (MB), one of the most common pediatric malignant brain tumors." (PMID 35573667, 2022). "Indeed, recent integrated analysis of SHH medulloblastomas with RNA-sequencing data demonstrated that each SHH subtype has a unique landscape of non-coding transcripts and biological processes and pathways related to cilium assembly and cell motility and were enriched in the SHHδ subtype." (PMID 35008416, 2022). "Thus, in theory adult SHH-activated medulloblastoma patients may benefit from vismodegib with improved response rates noted in almost half of patients when used in the recurrent setting as demonstrated in phase II trials." (PMID 36249063, 2022). "However, it may also depend on transcriptional upregulation, as in the case of Sonic Hedgehog (SHH)-dependent medulloblastoma." (PMID 34508175, 2021).
medulloblastoma (continued). "Moreover, we will discuss initial experiences in targeting new molecular alterations in gliomas, such as isocitrate dehydrogenase (IDH) mutations and neurotrophic tyrosine receptor kinase (NTRK) fusions, and in medulloblastomas such as the sonic hedgehog (SHH) pathway." (PMID 34360713, 2021). "Using medulloblastoma cells isolated from Math1-Cre/Ptch1fl/fl mice, it was shown that these cells autonomously cease proliferation and initiate differentiation, and the expression of all SHH pathway target genes significantly declines over time under adherent culturing conditions." (PMID 34436033, 2021). "Thus, although PI3K inhibition is a potential therapeutic target for ciliopathy in Joubert syndrome, it could have a detrimental effect in the context of SHH-driven medulloblastomas by sustaining ciliogenesis and driving proliferation." (PMID 31413155, 2019). "A similar analysis for each medulloblastoma subgroup showed that group 4 tumors demonstrate the lowest concordance, with a Spearman correlation mean of 0.16 compared to 0.30, 0.24, and 0.21 for group 3, SHH, and WNT respectively (four group comparison, Kruskal-Wallis test, p-value < 2.2e− 16)." (PMID 29880060, 2018). "Moreover, we performed complementary molecular and genomic analyses that support the hypothesis of a pro-tumorigenic SHH/AMPK/CNBP axis in medulloblastoma." (PMID 30360486, 2018). "The functions of the SHH signaling pathway have been previously explored in various types of human tumors, including B-cell lymphoma, malignant pleural mesothelioma, medulloblastoma, pancreatic cancer, prostate cancer, lung cancer, basal cell carcinoma, and chronic myelogeneous leukemia." (PMID 27039174, 2016). "Furthermore, since a constitutively active form of Smoothened mimics concentration-dependent actions of SHH, it would be of clinical interest to examine whether dual targeted inhibition of the SHH and ephrin-A5 impact medulloblastoma development." (PMID 26345456, 2015). "Moreover a recent report demonstrates that a rare population of Nestin-expressing progenitors (NEPs) reside in the cerebellum and exhibit decreased expression of DNA repair genes; upon aberrant activation of SHH signaling these NEP give rise to medulloblastoma tumors." (PMID 24796395, 2014). "Similarly, over-expression of associated network clusters enriched for SHH pathway members, GLI1, PTCH1 and PTCH2, was exclusive to human SHH medulloblastoma, and expression levels were significantly higher than in CD133+ NSCs, NPCs and all other controls used in this study." (PMID 25412507, 2014). "Furthermore, the Akt signalling pathway contributes to SHH-induced medulloblastoma formation." (PMID 19555497, 2009). "Recent molecular profiling has identified four principal medulloblastoma subgroups-WNT-activated, SHH-activated, Group 3, and Group 4-each demonstrating unique biological characteristics and clinical outcomes." (PMID 41899451, 2026). "Medulloblastoma is a severe pediatric brain tumor with distinct molecular subtypes-WNT, SHH, Group 3, and Group 4-each having unique genetic drivers and immune microenvironments." (PMID 42051512, 2026). "Medulloblastomas are classified into Wingless (WNT), Sonic Hedgehog (SHH), Group 3, and Group 4 molecular subtypes, each with a distinct tumor microenvironment and vascular architecture." (PMID 40948505, 2025). "Medulloblastoma (MB) is the most common malignant pediatric brain tumor; it is subgrouped into WNT, SHH, Group 3 (Grp3), and Group 4 (Grp4) MB1." (PMID 39762313, 2025).
medulloblastoma (continued). "Medulloblastomas are classified into four major molecular subgroups based on their transcriptional and epigenetic profiles: WNT-activated (WNT-MB), SHH-activated (SHH-MB), Group 3 (G3-MB), and Group 4 (G4-MB)." (PMID 39857430, 2025). "The Pediatric Brain Tumor Atlas (PBTA) cohort was filtered to include RNA-sequencing data from medulloblastoma samples classified by molecular subtypes: WNT, SHH, Group 3 (G3), and Group 4 (G4) (n = 254)." (PMID 39851951, 2025). "Background/Objectives: Medulloblastoma is the most common malignant brain tumor in children and comprises four molecular subtypes—WNT, SHH, Group 3, and Group 4—each with distinct genetic, epigenetic, and metabolic features." (PMID 40868156, 2025). "Medulloblastoma is highly heterogeneous, with distinct molecular subtypes (WNT, SHH, Group 3, and Group 4), each exhibiting unique biological characteristics, genetic profiles, and responses to treatment." (PMID 40868156, 2025). "Principal component analysis (PCA) based on the expression profiles of 642 ferroptosis-related genes effectively stratified the molecular subtypes of medulloblastoma (G3, G4, WNT, and SHH), as described in previous studies." (PMID 39857430, 2025). "To explore this possibility, we re-analyzed data from the Hugene11t platform (GEO ID: GSE85217), which includes 763 primary medulloblastoma samples classified into Group 3, Group 4, WNT, and SHH subtypes." (PMID 40701975, 2025). "In the case of the GSE37418 dataset, n = 73 pediatric medulloblastoma samples were analyzed, representing four expression classes, WNT-activated, SHH-activated, Group 3 and Group 4 medulloblastoma (WNT n = 8, SHH n = 10, G3 n = 16, G4 n = 39)." (PMID 40282457, 2025). "In medulloblastomas, according to the evidence, aberrant activation of RAS can influence the SHH (Sonic Hedgehog) pathway, promoting tumor growth." (PMID 40362343, 2025). "Using publicly available gene expression datasets of medulloblastoma (MB) subtypes, we identified a significant enrichment of specific ion channel genes in group 3 and 4 MBs compared to the WNT and SHH subtypes." (PMID 40150732, 2025). "Although considered a single disease, medulloblastoma encompasses four main molecular subgroups/subtypes—wingless (WNT), sonic hedgehog (SHH), Group3, and Group 4, each with unique transcription profiles, driver mutations, and prognosis." (PMID 39160595, 2024). "The medulloblastoma can be divided into four molecular subgroups (WNT, SHH, group 3 and group 4) with each of them having different characteristics." (PMID 38345610, 2024). "In medulloblastoma cell lines, AMPK activation inhibits the transcriptional activity induced by the canonical SHH pathway through GLI1 phosphorylation." (PMID 38539429, 2024). "At the same time, in addition to the SHH/PTCH pathway alterations, also the WNT signalling pathway was described in medulloblastomas." (PMID 39324445, 2024). "The molecular-based classification of medulloblastoma into WNT activated, SHH activated, group 3, and group 4 opened the door for research endeavors that aim to study the specific cellular, molecular, and neurodevelopmental characteristics of each subtype." (PMID 37568705, 2023). "All cases were molecularly classified into the four main medulloblastomas subgroups, namely, WNT activated (n=40, 15%), SHH activated (n=122, 46%), Group 3 (n=42, 16%), and Group 4 (n=62, 23%)." (PMID 37746264, 2023). "For example, if we look at the medulloblastoma subtypes from CBTN, there are 14 group 3, 49 group 4, 30 SHH, 9 WNT and 19 unclassified medulloblastoma samples." (PMID 36711972, 2023).